NFE2L3 (NFE2 like bZIP transcription factor 3)
Description:
Activates erythroid-specific, globin gene expression.
Synonyms: NRF3
Tractability: PROTAC: ubiquitination databases record sites on it.
Gene: Protein-coding gene on chromosome 7 (26,152,190 to 26,187,137, forward strand). Ensembl gene ENSG00000050344.
Subcellular location: Nucleus
Subcellular location (Human Protein Atlas): Nucleoplasm; Vesicles
Gene Ontology:
Molecular function: protein binding; DNA-binding transcription factor activity; DNA-binding transcription factor activity, RNA polymerase II-specific; RNA polymerase II cis-regulatory region sequence-specific DNA binding; DNA binding; DNA-binding transcription repressor activity, RNA polymerase II-specific
Biological process: integrated stress response signaling; regulation of transcription by RNA polymerase II; transcription by RNA polymerase II; negative regulation of transcription by RNA polymerase II; regulation of DNA-templated transcription
Cellular component: RNA polymerase II transcription regulator complex; chromatin; nucleus
Genetic constraint (gnomAD): Loss-of-function variants: 23 observed, 17.54 expected, observed/expected ratio (o/e) 1.31, 90% interval 0.94 to 1.8. The synonymous counts are far from expectation, so gnomAD's model fits this gene poorly and the ratio says little. Missense variants: 1,106 observed, 743.8 expected, observed/expected ratio (o/e) 1.49, 90% interval 1.41 to 1.56. Synonymous variants: 405 observed, 287.82 expected, observed/expected ratio (o/e) 1.41, 90% interval 1.3 to 1.53.
Homologues: Orthologues: chimpanzee NFE2L3 (98% identical), macaque NFE2L3 (93% identical), pig NFE2L3 (79% identical), dog NFE2L3 (78% identical), rabbit NFE2L3 (71% identical), guinea pig NFE2L3 (69% identical), mouse Nfe2l3 (67% identical), rat Nfe2l3 (64% identical), tropical clawed frog nfe2l3 (45% identical), zebrafish nfe2l3 (24% identical). Paralogues in human: NFE2L1 (32% identical), NFE2L2 (21% identical), NFE2 (17% identical).
Diseases named in the same sentence as NFE2L3 in open-access papers:
NFE2L3 is named in the same sentence as 88 diseases in open-access papers, as found by Europe PMC text mining. Sharing a sentence is not in itself a finding about the gene and the disease. The quoted sentences say what the papers report.
colon cancer (19 papers, 2012 to 2025). "Recent studies have confirmed that NFE2L3 is linked to certain cancers in humans, including colon cancer, bladder cancer, breast cancer, pancreatic cancer, and liver hepatocellular carcinoma." (PMID 35846126, 2022). "Both in vitro and in vivo experiments have demonstrated that knocking down NFE2L3 leads to a reduction in the proliferation of colon cancer cells, thereby inhibiting tumor growth." (PMID 39149514, 2024). "Of note, knockdown NFE2L3 showed a significant increase in the protein levels of NFE2L1 in colon cancer cells, implying a complex regulatory relationship between NFE2L3 and proteasome activity." (PMID 39149514, 2024). "The overexpression of NFE2L3 promotes proliferation and metastasis in hepatocellular carcinoma and colon cancer." (PMID 35810383, 2022). "Our study also demonstrated that NFE2L3 expression was associated with patient survival in multiple ICB cohorts, and that knockdown of NFE2L3 improved the effect of ICB treatment for colon cancer in the Kearney 2018 NK_10 cohort." (PMID 35846126, 2022). "Recently, it was shown that knockdown of NFE2L3 reduced human colon cancer cell proliferation through an increase in the levels of DUX4, a protein that functions as a CDK1 inhibitor." (PMID 35091681, 2022). "NFE2L3 functioned as an oncogene in colon cancer by suppressing the expression of DUX4, which functioned as a direct inhibitor of CDK1." (PMID 35059466, 2022). "Notably, NFE2L3 has paradoxical roles depending on the cellular context: although murine models suggest its anti-inflammatory and tumor-restraining effects in colon cancer, human studies indicate its pro-oncogenic functions in other malignancies." (PMID 40963625, 2025). "Increased expression of NFE2L3 is seen in ulcerative colitis and colon cancer." (PMID 35323693, 2022). "NFE2L3 may modulate the tumor microenvironment and control colon cancer cell growth." (PMID 41440381, 2025). "This pro-inflammatory microenvironment is a key contributor to cancer development.The NFE2L3 transcription factor bridges NF-κB signaling to CDK1 activation, promoting the proliferation of colon cancer cells." (PMID 40595862, 2025). "Another study showed that the β-catenin/Tcf4 complex promoted the proliferation of colon cancer cells and upregulated GLUT1 expression by upregulating the expression of NFE2L3 mRNA." (PMID 35846126, 2022). "Research also demonstrated that NFE2L3 functions as a critical regulator in a pathway that links NF-κB signaling to control CDK1 activity, thereby driving colon cancer cell proliferation." (PMID 35211477, 2021). "In an initial attempt to evaluate CTHRC1 and NFE2L3 as biomarkers for cancer and the obtained antibodies for their identification, the DAS- ELISA was used to measure CTHRC1 and NFE2L3 in colon cancer cells using known colon cancer cell lines as a model." (PMID 22321245, 2012). "Finally, not all colorectal cancer subtypes in humans are linked to inflammation, as our recent findings in human colorectal carcinoma cells showed that NFE2L3 promotes colon cancer cell proliferation in vitro regardless of the immune context." (PMID 35091681, 2022). "In the mouse, the Nfe2l3 gene has been shown to be significantly upregulated in the colonic mucosa of mice following AOM/DSS treatment, yet its function in inflammation-induced colon cancer has not been investigated." (PMID 35091681, 2022).
colorectal cancer (19 papers, 2012 to 2025). A primary or metastatic malignant neoplasm that affects the colon or rectum. "A study has also shown that loss of NFE2L3 protects against inflammation caused by colorectal cancer by modulating TME52." (PMID 39149248, 2024). "Recently, a series of studies linked the NFE2L3 transcription factor to colorectal cancer yet its role in cancer progression remains to be explored." (PMID 35091681, 2022). "In the same way, the relation of NFE2L3 to cancer was studied by other investigators, showing that 20 genes, including the gene encoding NFE2L3, were up-regulated in colorectal cancer cells and in adenomas when compared with normal tissues." (PMID 22321245, 2012). "NFE2L3 is highly expressed in Hodgkin’s lymphoma, pancreatic cancer, hepatocellular carcinoma, gastric cancer, colorectal cancer and other malignant tumours." (PMID 40169553, 2025). "Recent studies have shown that NFE2L3 is increased in colorectal cancer and has a positive correlation between NFE2L3 expression in tumor grade and stage." (PMID 39149514, 2024). "Using this model, we discovered that the presence of NFE2L3 promotes colorectal cancer progression through modulation of the tumor microenvironment and enhancing the inflammatory response." (PMID 35091681, 2022). "In upcoming studies, it will be of interest to investigate the role of NFE2L3 in other colorectal cancer models, such as the ApcMin/+ mice, to gain a better understanding of NFE2L3 function in the pathogenesis of various CRC molecular subtypes." (PMID 35091681, 2022). "We investigated the role of the NFE2L3 transcription factor in inflammation-induced colorectal cancer." (PMID 35091681, 2022). "In colorectal cancer, NFE2L3 expression in tumor tissues was significantly higher than that in paired paracancerous tissues, and inhibition of NFE2L3 expression also caused tumor cell proliferation to arrest in the G0/G1 phase." (PMID 34783304, 2021). "The survival rate of patients with colorectal cancer is extremely low in those with high expression of NFE2L3." (PMID 33123284, 2020). "The function of NFE2L3 in the development of pancreatic cancer, colorectal cancer and other malignant tumors has been confirmed, and it is related to the occurrence of carcinogen-induced lymphoma in mice 9,12,13." (PMID 33123284, 2020). "NFE2L3 (nuclear factor, erythroid 2-like 3) was among those overlapped DEGs and was rarely reported in colorectal cancer." (PMID 31191746, 2019). "In the COADREAD expression dataset, NFE2L3 was markedly upregulated in colorectal cancer samples compared with normal samples (p < 0.0001), validated by our real-time PCR assay in 48 paired paratumor and tumor samples (p < 0.0001)." (PMID 31191746, 2019). "In this study, we verified that NFE2L3 mRNA expression was upregulated in colorectal cancer samples when compared to adjacent samples." (PMID 31191746, 2019). "In conclusion, NFE2L3 could serve as a valuable biomarker or therapeutic target in the context of colorectal cancer." (PMID 39149514, 2024). "While we established a role for NFE2L3 in the promotion of inflammation-induced colorectal cancer, it is unclear whether the observed phenotype is due to loss of NFE2L3 within the colonic cells and/or the immune cells or both." (PMID 35091681, 2022). "In colorectal cancer, NFE2L3 regulates the growth of CRC via the NF-κB pathway." (PMID 36337840, 2022). "Therefore, we sought to examine the role of NFE2L3 in inflammation-induced colorectal cancer following treatment with AOM/DSS." (PMID 35091681, 2022). "Although elevated NFE2L3 levels correlated with protective roles during breast cancer and T-cell lymphoma, it had the opposite effect in thyroid, pancreas, hepatocellular and colorectal carcinoma." (PMID 35091681, 2022).
colorectal cancer (continued). "In colorectal cancer, NFE2L3 is reported to promote cell proliferation." (PMID 31191746, 2019). "In summary, we found that NFE2L3 was upregulated in colorectal cancer." (PMID 31191746, 2019). "This might suggest that the same case happened in colorectal cancer cells where CCND1 is regulated by NFE2L3 in colorectal tissue samples." (PMID 31191746, 2019). "Moreover, studies have shown that the overexpression of CDK1 in colorectal cancer, and the authors found that the decreased proliferation of colorectal cancer cells after NFE2L3 knockout may be due to the decreased CDK1 activity." (PMID 34586751, 2021).
breast carcinoma (16 papers, 2014 to 2026). "Thymidine kinase-1 (TK1), lysyl oxidase (LOX), lysine demethylase 5B (KDM5B), proteasome 26S subunit non-ATPase 4 (PSMD4), and nuclear factor erythroid 2-like 3 (NFE2L3) genes are implicated in relapse and poor prognosis of patients with breast cancer." (PMID 37767092, 2023). "Studies have shown that the prognostic model genes TK1, LOX, KDM5B, PSMD4, and NFE2L3 are associated with breast cancer progression, prognosis stratification, and clinical drug resistance." (PMID 37767092, 2023). "In conclusion, NFE2L3 was confirmed as a direct downstream target gene of miR-1246 in human breast cancer cells." (PMID 34926237, 2021). "Specifically, when NFE2L3 was inhibited in breast cancer tissues, the proliferation and metastasis of breast cancer cells was reduced." (PMID 34783304, 2021). "In combination, the present data revealed that the miR-1246/NFE2L3 axis critically affected the malignant properties of human breast cancer cells, at least partially through regulating the activation of several signaling pathways." (PMID 34926237, 2021). "In conclusion, the present study provided novel insight into the drug resistance and migration of human breast cancer cells via the miR-1246/NFE2L3 axis." (PMID 34926237, 2021). "NFE2L3 mRNA levels were found to be up-regulated in human breast cancer cells and testicular carcinoma tissue samples." (PMID 24676469, 2014). "It was also investigated whether nuclear factor (erythroid 2)-like factor 3 (NFE2L3) is a novel target gene of miR-1246 in human breast cancer cells, and whether its overexpression or silence could affect Doc resistance, cell migration and invasion of breast cancer cells, and the role of miR-1246." (PMID 34926237, 2021). "Therefore, miR-1246 may promote drug resistance and metastasis in breast cancer by targeting NFE2L3." (PMID 34926237, 2021). "However, the functions of NFE2L3 in human breast cancer remain poorly understood to date." (PMID 34926237, 2021).
hepatocellular carcinoma (10 papers, 2020 to 2025). A malignant tumor that arises from hepatocytes. "High mRNA and protein levels of NRF3 are associated with advanced TNM stages with a poor survival in pancreatic cancer, and high NFE2L3 mRNA is associated with a higher grade and stage in hepatocellular carcinoma." (PMID 35378827, 2022). "NFE2L3 has turned out to be associated with oxidative stress, but the relevance of NFE2L3 in hepatocellular carcinoma (HCC) has remained elusive." (PMID 33123284, 2020). "In summary, these results indicate that NFE2L3 plays an important role in regulating the occurrence, development, and prognosis of hepatocellular carcinoma." (PMID 39149514, 2024). "NFE2L3 promoted cell proliferation and metastasis of hepatocellular carcinoma through activation of the Wnt/β-catenin pathway." (PMID 35059466, 2022). "In multiple previous studies, somatic mutations of NFE2L2, the homolog of NFE2L3, was detected in plasma cell-free DNA (cfDNA) in hepatocellular carcinoma (HCC) and lung squamous cell carcinoma (LUSC), and was regarded as a non-invasive biomarker for tumor risk prediction and overall survival." (PMID 35664314, 2022). "IHC showed that NFE2L3 protein expression was also increased in hepatocellular carcinoma tissues." (PMID 33123284, 2020). "However, few articles have involved the functions of its homologous gene NFE2L3 in cancer development especially in hepatocellular carcinoma." (PMID 33123284, 2020). "Therefore, targeting NFE2L3 may be an important strategy for the treatment of hepatocellular carcinoma." (PMID 39149514, 2024). "Interestingly, in hepatocellular carcinoma (HCC) the nuclear factor erythroid 2-like 3 (NFE2L3), which has been largely involved in cancer development, induces the expression of ISG15 by binding to the antioxidant response element (ARE) located in the ISG15 promoter." (PMID 38400136, 2024).
pancreatic cancer (7 papers, 2020 to 2025). "High expression of NFE2L3 predicted poor prognosis of pancreatic cancer." (PMID 35059466, 2022).
clear cell renal cell carcinoma (5 papers, 2019 to 2025). "Upregulation of transcriptional levels could be explained epigenetically, since hypomethylation of the NFE2L3 gene is associated with higher NFE2L3 mRNA levels in renal clear cell carcinoma." (PMID 35378827, 2022). "Findings showed that NFE2L3 expression was higher in clear cell carcinoma of the kidney (KIRC) than in normal tissue." (PMID 39149514, 2024). "Methylated hub genes, including HOXD3, LAT, and NFE2L3, were proved to be a novel prognostic indicators in clear cell renal cell carcinoma." (PMID 32296463, 2020). "In summary, our results suggest that NAT10 mediates ac4C acetylation of NFE2L3 mRNA, promotes its mRNA stability, regulates the LASP1-AKT/GSK3β/β-catenin axis and promotes the progression of renal clear cell carcinoma." (PMID 40169553, 2025). "For the survival analysis, we found that hypomethylation and over-expression of LAT and NFE2L3 were correlated with poor survival, while hypermethylation and low-expression HOXD3 was correlated with poor survival of clear cell renal cell carcinoma patients." (PMID 31777602, 2019).
gastric cancer (5 papers, 2021 to 2025). A primary or metastatic malignant neoplasm involving the stomach. "They analyzed the DNA methylation characteristics of gastric cancer using public databases and identified 10 candidate genes, including NFE2L3, that were associated with gastric cancer recurrence." (PMID 39149514, 2024). "Over the years, numerous experts have confirmed that EMT is significantly associated with the metastasis of gastric cancer and can potentially enhance the migratory capability of gastric cancer cells by inducing the upregulation of NFE2L3 or PADI4." (PMID 38149985, 2023). "We utilized data from databases and clinical gastric cancer specimens to validate the aberrant expression level of NFE2L3 and further assessed the clinical value of NFE2L3." (PMID 38514488, 2024). "They observed that NFE2L3 expression in gastric cancer tissues was significantly higher than that in the adjacent tissues." (PMID 39149514, 2024). "NFE2L3 expression level in gastric cancer cells was observed to be higher compared with normal gastric mucosal epithelial cells." (PMID 38514488, 2024). "In summary, NFE2L3 is highly expressed in gastric cancer and promotes gastric cancer cell proliferation and metastasis and the EMT process." (PMID 34783304, 2021). "In our study, we explored NFE2L3 expression in gastric cancer for the first time, constructed an NFE2L3 knockdown cell line to verify the effect of NFE2L3 on gastric cancer cell proliferation and metastasis, and assessed the cell cycle and apoptosis." (PMID 34783304, 2021). "The results showed that NFE2L3 was highly expressed in gastric cancer tissues and promoted gastric cancer cell proliferation and metastasis." (PMID 34783304, 2021). "In gastric cancer cells with NFE2L3 knockdown, E-cadherin expression was significantly upregulated, whereas vimentin and N-cadherin expression was inhibited." (PMID 34783304, 2021). "Moreover, the knockdown of NFE2L3 led to inhibited cellular biological behaviors such as proliferation, migration, and invasion of gastric cancer cells, along with cell cycle arrest and increased apoptosis." (PMID 39149514, 2024). "We further confirm this speculation in gastric cancer tissues and cell lines, the qRT-PCR results showed significant levels of NFE2L3." (PMID 38514488, 2024). "In addition, in vivo results suggest that NFE2L3 may act as an oncogene roles in gastric cancer through promoting the gastric cancer cells growth and migration." (PMID 38514488, 2024). "Finally, we may need to establish an animal model to further study the relationship between NFE2L3 and gastric cancer in vivo." (PMID 34783304, 2021). "Further studies revealed that E-cadherin expression was upregulated, whereas vimentin and N-cadherin expression were downregulated, suggesting a possible connection between NFE2L3 and EMT in gastric cancer." (PMID 39149514, 2024). "To investigate the potential molecular mechanism of NFE2L3, we analyzed the correlation of NFE2L3 with immune molecular mechanisms, constructed PPI network, performed GO analysis and KEGG analysis, and finally explored the biological function of NFE2L3 in gastric cancer cells." (PMID 38514488, 2024).
glioblastoma (5 papers, 2019 to 2024). The most malignant astrocytic tumor (WHO grade IV). "Furthermore, research has linked NFE2L3 to other cancers such as lung adenocarcinoma, malignant pleural mesothelioma, ovarian cancer, glioblastoma multiforme, and laryngeal carcinoma, indicating its potential as a target for innovative cancer treatment approaches." (PMID 39149514, 2024).
colorectal adenocarcinoma (4 papers, 2019 to 2024). The most common type of colorectal carcinoma. "In this regard, we focused on the transcription factor NRF3 (NFE2L3), because it is highly expressed in several cancers, including colorectal adenocarcinoma, and is correlated with poor prognosis." (PMID 31288376, 2019). "Moreover, comparing the samples from young and old donors, four DEGs (HOXB5, KRT8, MSX1, NFE2L3) in the samples from old donors were specifically expressed in colorectal adenocarcinoma (4/33, 12%)." (PMID 38520027, 2024).